KRAS (KRas proto-oncogene, GTPase)
Diseases named in the same sentence as KRAS in open-access papers (continued):
Sharing a sentence is not in itself a finding about the gene and the disease.
cancer (continued). "The three main RAS genes mutated in cancer are HRAS, KRAS, and NRAS." (PMID 38982514, 2024). "Consequently, this research endeavor elucidates the landscape of KRAS-mutant cancers, serving as a catalyst for intensified exploration by the scientific community, particularly in light of the escalating incidence of cancer." (PMID 38706597, 2024). "Remarkably, our study unexpectedly discovered that KRAS G12C–mutant cancer cells, whether they exhibit intrinsic or acquired resistance to KRAS G12C inhibitors, also display cross-resistance to other inhibitors targeting EGFR, IGF1R, MEK, or SHP2." (PMID 39704172, 2024). "In addition, to increase the antitumor effect because the efficacy of TAK-981 monotherapy was modest in vivo we next focused on the co-inhibition of SUMOylation and MEK because the MAPK pathway plays critical roles in KRAS-mutant cancer." (PMID 38992694, 2024). "For instance, cancer‐related mutations (KRAS or BRAF) in CRAs failed to be detected in plasma samples using droplet digital PCR,21, 22 Moreover, a model relying on six methylation markers cannot identify CRAs unless the median tumor size exceeds 1.5 cm." (PMID 39554798, 2024). "Therefore, combining KRAS G12C inhibitors with other cancer treatments has been studied, and we see more and more evidence recently." (PMID 38756650, 2024). "Thus, targeting KRAS for cancer treatment remains challenging, particularly in overcoming chemoresistance." (PMID 39850800, 2024). "KRAS with the G12D mutation modulates translation via the MNK/eIF4E pathway and results in sustained expression of c-MYC, a common proto-oncogene involved in many cancers." (PMID 38481800, 2024). "Furthermore, lactate is a metabolic byproduct of KRAS-mutant metabolism in cancer cells and can create an immunosuppressive TME." (PMID 38481800, 2024). "Furthermore, the positive regulatory feedback loop between miR-21 and members of the KRAS mutant in ovarian cancer illustrates the critical role of miR-21 in cancer cell proliferation." (PMID 38891080, 2024). "Both adagrasib and sotorasib are developed to target the KRAS(G12C)-mutant by covalently binding to the mutant cysteine residue in KRAS(G12C), leading to irreversible inhibition of the KRAS activity and blocking KRAS downstream signaling pathways essential for cancer cell proliferation." (PMID 39850800, 2024). "The function of wild-type KRAS in KRAS mutant cancers remains to be explored." (PMID 38168062, 2024). "KRAS acts as both a prognostic and predictive marker in various types of cancer." (PMID 39056802, 2024). "A notable feature of KRAS mutant cancers, including those of the pancreas, colon, and lung, is that they can be either KRAS-dependent or KRAS-independent, based on the degree of their addiction to canonical KRAS signaling." (PMID 38573819, 2024). "The limitation of our study is related to the sample size because examining a large number of cancer patients for the KRAS gene, HPV, and EBV infections could provide results that are generalizable to the population." (PMID 39673361, 2024). "This role of KRAS could be exploited, since targeting cancer stem cells to prevent cancer recurrence remains one of the most significant challenges in oncology." (PMID 39061234, 2024). "There are also alternative therapeutic methods for patients with KRAS-mutated cancers that are not based on the direct blockade of signaling pathways." (PMID 38397927, 2024). "Inhibition of downstream signaling and proliferation is limited to cancer cells carrying a KRAS mutation, and treatment with the drug prevents the growth of mutant KRAS tumors in mice without any detrimental effect on animal weight." (PMID 39456549, 2024). "Targeting SRC overcomes G12Ci resistance in KRAS-G12C mutant cancers." (PMID 39661665, 2024). "For example, approximately 25% of mutations in human cancer are related to KRAS, but KRAS-targeted therapeutic agents are lacking." (PMID 38193944, 2024).
cancer (continued). "It is possible that supplements such as epidermal growth factor (EGF) in our culture medium may substitute for oncogenic KRAS to induce pre-cancer signatures in organoid culture." (PMID 38280869, 2024). "Evidence shows that KRAS plays a role in rewiring metabolic pathways and regulating estrogen receptor signaling, highlighting the relevance of these factors when considering treatment for cancers in females." (PMID 38886847, 2024). "Top 10 most productive institutions in the research of KRAS-related cancer during 2013 to 2022." (PMID 38706597, 2024). "This scenario was also observed in KRAS G12D–mutant cancer cells." (PMID 39704172, 2024). "Therefore, new therapeutic strategies are required to delay and overcome KRAS resistance in cancer patients." (PMID 38191673, 2024). "Although there is no direct correlation between HPV and KRAS mutations, both can independently contribute to the development of different types of cancer." (PMID 39673361, 2024). "Top 10 most locally cited references in the research of KRAS-related cancer during 2013 to 2022." (PMID 38706597, 2024). "In addition to regulating the cancer stem cell phenotype, CAFs can also alter the proteome profile associated with CRC cells harboring a KRAS mutation." (PMID 39061234, 2024). "This study investigates whether CAF-secreted factors induce resistance to KRAS inhibition by enhancing cancer stemness." (PMID 39061234, 2024). "Because transcriptional programs induced by Hh signal depend on the GLI transcription factor, we tested whether GLI-1 mediates the re-expression of KRAS in cancer cells treated with a KRASG12C inhibitor." (PMID 38225225, 2024). "However, none of these preclinical investigations or clinical trials has employed farnesyl-transferase inhibitors, likely due to the long history of the failures of FTis as monotherapies in KRAS mutant cancers." (PMID 38278976, 2024). "Moreover, the journal Clinical Cancer Research ranked first in IF and h-index in KRAS-related cancer research." (PMID 38706597, 2024). "The prevalence of the G12D oncogenic mutation is much higher than others including G12C in pancreatic cancer and lung cancer, but no inhibitor has been approved for the KRAS (G12D)-mutated cancer." (PMID 39749200, 2024). "Ectopic expression of AURKA also blocked ARS-1620–induced KRAS promoter activity in cancer cells." (PMID 38225225, 2024). "Activating the P21 protein through KRAS gene editing sensitizes cancer cells to chemotherapy." (PMID 38195537, 2024). "Additionally, RMC-7977 inhibited the growth of KRASG12C cancer models that are resistant to KRAS(G12C) inhibitors owing to restoration of RAS pathway signalling." (PMID 38589574, 2024). "Elevated thrombin, which is linked to worse cancer outcomes, activates PAR-1 receptors on both platelets and cancer cells which promote tumor growth, invasion, and survival as shown with the progression of KRAS mutant CRC via the PAR1-PDK1-AKT signaling pathway." (PMID 39114075, 2024). "As the field evolves, ongoing research into KRAS mutations and their role in cancer progression will continue to inform the development of TCR-T cell therapies, potentially expanding their application to a broader range of cancer types." (PMID 39439803, 2024). "Oncogenic KRAS decouples glucose and glutamine metabolism to support cancer cell growth." (PMID 39466877, 2024). "Here, we used genetic analyses to identify STAT3 as a relevant dependency in KRAS-driven cancer." (PMID 38573819, 2024). "Our findings indicate that dual inhibition of SUMOylation and MEK may be a promising treatment for MYC-expressing KRAS-mutant cancers by enhancing DNA damage accumulation." (PMID 38992694, 2024).
cancer (continued). "This phenotype is concordant with the mutual exclusivity of activating mutations within KRAS and BRAF in patient CRC samples (P < 0.001), highlighting that the drug addiction phenotype is dependent on pre-existing mutations in the cancer cell." (PMID 39424923, 2024). "Even wildtype KRAS has a strong proliferative drive on cancer cells." (PMID 39201772, 2024). "Interestingly, some metabolites identified in PANC1 compared to BxPC3 were oppositely regulated by TRPML1 inhibition, suggesting their potential as biomarkers for KRAS-mutant cancer cells." (PMID 38672219, 2024). "Therefore, HSF1 represents a promising target for KRAS-mutant cancers, potentially addressing some resistance mechanisms by disrupting cancer cell stress responses." (PMID 39850800, 2024). "Since MAPK inhibition of the KRAS downstream pathway is crucial in KRAS-mutant cancer, we expected that co-inhibition of SUMOylation and MEK might be a good option." (PMID 38992694, 2024). "Thus, KRAS was deemed “undruggable”, and developing drugs to target KRAS became one of the Holy Grails of cancer research." (PMID 38800401, 2024). "Notably, increased reliance on glutamine is a well-documented metabolic vulnerability in KRAS-mutant cancers." (PMID 38668053, 2024). "This suggests that FAK could potentially serve as an effective biomarker for cancer development induced by abnormal KRAS signaling." (PMID 38410129, 2024). "KRAS is one of the most common oncogenes in numerous cancers." (PMID 38481800, 2024). "The loss or dysfunction of CCDC6 could exacerbate the oncogenic effects of KRAS, as impaired DDR would allow for the unchecked accumulation of mutations, fueling cancer progression." (PMID 39684377, 2024). "Furthermore, many additional inhibitors are currently being evaluated for their clinical efficacy, including a pan-KRAS inhibitor that targets many of the mutants present in human cancers." (PMID 39379700, 2024). "His cancer is associated with a CHEK2 gene mutation and is HER-2 IHC3+ and KRAS G12D positive." (PMID 39221315, 2024). "For inhibitors of the m6A-recognition protein, a compound called “7,773” has been found to bind IGF2BP1 and inhibit its interaction with KRAS RNA, thereby reducing the expression of KRAS protein and downstream signaling, inhibiting the cancer-promoting activity of IGF2BP1." (PMID 38343637, 2024). "Additionally, resistance mechanisms revealed in KRAS G12C mutant tumors have been observed following MRTX1133 treatment in G12D mutant cancer models." (PMID 39687047, 2024). "Taken together, our data reveal that the Hippo-YAP/TAZ pathway is critical in conferring and sustaining resistance to KRAS inhibitors, and modulation of this pathway holds promise for overcoming resistance to KRAS inhibitors and improving outcomes for patients with KRAS-mutant cancers." (PMID 39704172, 2024). "This outcome aligns with our previous concerns that cancer cells acquiring resistance to KRAS G12C inhibitors may also develop cross-resistance to SHP2 inhibitors as well as other inhibitors targeting upstream or downstream of the RAS signaling pathway." (PMID 39704172, 2024). "We next tested whether ectopic expression of AURKA blocks the induction of Hh signal-related genes and the re-expression of KRAS in cancer cells treated with a KRASG12C inhibitor." (PMID 38225225, 2024). "Furthermore, BI-3406 can weaken the feedback reactivation induced by MEK inhibitors, thereby enhancing the sensitivity of KRAS-dependent cancers to MEK inhibition." (PMID 38734764, 2024). "Moreover, changes in the cancer methylome are coupled with somatic mutations in cancer driver genes, such as CTNNB1, ERBB2, KRAS, and PIK3CA, which consistently recapitulate the somatic evolutionary process and consequential clonality of cancers." (PMID 38566132, 2024).
cancer (continued). "Considering the role of Hh signaling in the expression of genes involved in cell proliferation, it is possible that upregulation of Hh signaling may play a role in re-expression of KRAS in KRASG12C inhibitor–treated cancer cells." (PMID 38225225, 2024). "Top 10 most productive journals in the research of KRAS-related cancer during 2013 to 2022." (PMID 38706597, 2024). "The most promising TCRs warrant testing in patients with KRAS G12V–positive cancers." (PMID 39484723, 2024). "Among different RAS isotypes, KRAS is the prevalent mutation associated with different types of cancer, namely, pancreatic, colorectal, and lung carcinoma, while the incidence of NRAS and HRAS mutation is less among these three types of cancer." (PMID 39056802, 2024). "Previous in vitro and in vivo studies in immune-compromised mice demonstrated that SOS1i reduced the formation of GTP-loaded RAS, limited cellular proliferation of human tumors driven by various KRAS mutations, and enhanced MEK inhibition in KRAS-dependent cancers." (PMID 38727236, 2024). "Besides, China stood out among developing nations in the study of KRAS-mutant cancer, for it was the only developing nation to be included on the list." (PMID 38706597, 2024). "Research into the use of KRAS inhibitors in other cancers is also in progress." (PMID 38397927, 2024). "Next, we discuss therapeutic strategies to inhibit KRAS and explore the mechanisms by which cancers develop resistance, whether through on-target, off-target, or non-mutational alterations." (PMID 38668053, 2024). "Additionally, mechanisms behind the development of resistance to KRAS p.G12C inhibitors allow cancer cells to evade targeted therapies." (PMID 39001451, 2024). "Mutant-selective inhibitors of KRASG12D and pan-KRAS inhibitors could potentially expand the therapeutic landscape beyond KRASG12C mutant cancers." (PMID 38593348, 2024). "Targeting the KRAS signaling pathway and angiogenesis may be a promising strategy for developing new cancer treatments." (PMID 38481800, 2024). "Designing prospective clinical SMARCA4-mutated or SMARCA4/KRAS co-mutated NSCLC trials to evaluate targeted therapies and immunotherapy may lead to a better understanding of how to improve cancer patients’ outcomes and survival rates." (PMID 39063938, 2024). "Targeting HSF1 in KRAS-mutant cancers, such as PDAC and NSCLC, where chemoresistance is common and therapeutic options are limited could open new avenues for treatment." (PMID 39850800, 2024). "As an upstream regulator of RAS, EGFR is integral to KRAS-driven cancers." (PMID 39770538, 2024). "KRAS mutation testing in SCC is currently not widely recommended, since the KRAS mutation occurrence rate in this cancer subtype is low (4–8%)." (PMID 38397927, 2024). "These non-selective site effects could have compromised the therapeutic effect of targeting KRAS, as these mutations could inactivate NF1 and thus promote cancer growth." (PMID 38195537, 2024). "It is likely that these agents will show a higher level of toxicity but may have a role in treating cancers driven by wild-type KRAS or amplified KRAS." (PMID 38576709, 2024). "Similarly, in colorectal KRAS-mutant cancer cells, trametinib downregulates Mcl-1 levels in a ubiquitin–proteasome-dependent manner through E3 ligase activation." (PMID 38643157, 2024). "However, further development and optimization are necessary to assess its efficacy in KRAS mutant cancers before advancing to clinical trials." (PMID 39850800, 2024). "Membrane‐anchored KRAS molecules self‐associate to act as scaffolds for promoting the functional dimerization of downstream RAF kinases, which are implicated in a quarter of all human cancers." (PMID 39138901, 2024).
cancer (continued). "Kirsten rat sarcoma viral oncogene homolog (KRAS), a member of the rat sarcoma viral oncogene (RAS) family, is the most frequently mutated oncogene in human cancer, with a prevalence of 25–30% of all human cancer cases." (PMID 38397927, 2024). "Among central nodes were ERBB2 (v-erb-b2 avian erythroblastic leukemia viral oncogene homolog 2), CRK (Cysteine-rich receptor-like-kinase), HRAS, and KRAS (Kirsten rat sarcoma virus), all of which were proto-oncogenes involved in the development of various cancer types." (PMID 38304545, 2024). "Of note, however, additional irradiation was found to confer pronounced additional reduction in clonogenicity in both of the KRAS mutant cancer cell lines tested, suggesting potential therapeutic efficacy of KRAS inhibition by BI-3406 in combination with MEK inhibition and irradiation." (PMID 38892436, 2024). "We found that MYC downregulation occurred via SUMOylation inhibition in KRAS-mutant cancer cells." (PMID 38992694, 2024). "For KRAS-driven cancers, two seminal studies have greatly contributed to popularizing this field." (PMID 39390257, 2024). "Single-chain variable fragments (scFv) for KRAS-HLA complexes have been generated and there is a study converting these scFvs to the single-chain diabody which can induce T cell activation and kill target cancer cells." (PMID 38752985, 2024). "Principal component analysis (PCA) score plots for both ESI-positive and ESI-negative modes demonstrated a clear separation between BxPC3 and PANC1 cells, further supported by hierarchical condition trees that effectively clustered cancer samples based on their KRAS status." (PMID 38672219, 2024). "Evidence suggests that GC1 plays a key role in mutant KRAS-driven metabolic reprogramming of cancer cells through multiple mechanisms, including enhanced glutaminolysis, maintenance of redox homeostasis, and epigenetic regulation of genes involved in cell growth, proliferation, and stemness." (PMID 39795950, 2024). "Top 10 most productive authors in the research of KRAS-related cancer during 2013 to 2022." (PMID 38706597, 2024). "Collectively, we discovered a new application of the novel pan-KRAS inhibitor — BI-2865 in reversing MDR in cancers, and systematically confirmed that BI-2865 significantly, safely and selectively enhanced the chemotherapeutic efficacy in the P-gp induced MDR tumors both in vitro and in vivo." (PMID 38872211, 2024). "Targeting KRAS has been a major focus of cancer research over the past four decades." (PMID 39456549, 2024). "The findings indicated that these new hits may be KRAS G12D protein inhibitors, which may be important for cancer treatment." (PMID 38794122, 2024). "The RAS-regulated ERK1/2 signalling pathway is frequently activated in cancer and developmental syndromes (RASopathies) due to activating mutations in a variety of pathway components including the RAS proteins (especially KRAS), BRAF, CRAF, MEK1 and MEK2." (PMID 38381045, 2024). "KRAS G12D-specific TCR-T cells effectively recognize and kill cancer cells carrying this mutation." (PMID 39439803, 2024). "In addition to this spectrum of oncogenic KRAS mutations, evaluation of specific pro- or anti-tumourigenic roles for the wild-type RAS proteins in the context of oncogenic RAS across cancer types has been controversial." (PMID 38168062, 2024). "Thus, Gln deprivation creates a “synthetic lethality” for capecitabine, paclitaxel, and rapamycin in KRAS-driven cancer cells." (PMID 39272883, 2024). "Functional analysis further revealed that KRAS mutations led to upregulation of WNT, MAPK, and IL-6/JAK/STAT signaling pathways, which are known to facilitate cancer cell proliferation, growth, and invasion, resulting in more aggressive disease and reduced treatment response." (PMID 38783092, 2024). "KRAS mutant cancers represent highly malignant human cancers with poor outcomes." (PMID 38473779, 2024).